ZNF83 (zinc finger protein 83)
Description:
May be involved in transcriptional regulation.
Synonyms: ZNF816B; FLJ11015; HPF1
Tractability: PROTAC: ubiquitination databases record sites on it.
Gene: Protein-coding gene on chromosome 19 (52,612,356 to 52,638,388, reverse strand). Ensembl gene ENSG00000167766.
Subcellular location: Nucleus
Subcellular location (Human Protein Atlas): Nucleoplasm
Gene Ontology:
Molecular function: protein binding; DNA-binding transcription factor activity, RNA polymerase II-specific; RNA polymerase II cis-regulatory region sequence-specific DNA binding
Biological process: regulation of transcription by RNA polymerase II
Cellular component: nucleus
Genetic constraint (gnomAD): Loss-of-function variants: 0 observed, 0.16 expected, observed/expected ratio (o/e) 0, 90% interval 0 to 1.88. That is too few expected variants to judge how well the gene tolerates losing a copy. Missense variants: 552 observed, 648.73 expected, observed/expected ratio (o/e) 0.85, 90% interval 0.79 to 0.91. Synonymous variants: 209 observed, 217.13 expected, observed/expected ratio (o/e) 0.96, 90% interval 0.86 to 1.08.
Homologues: Orthologues: macaque ZNF83 (85% identical). Paralogues in human: ZNF880 (57% identical), ZNF528 (54% identical), ZNF836 (47% identical), ZNF841 (47% identical), ZNF546 (45% identical), ZNF658 (45% identical), ZNF616 (45% identical), ZNF678 (44% identical), ZNF28 (44% identical), ZNF33A (43% identical), ZNF41 (42% identical), ZNF600 (42% identical), and 164 more.
Diseases named in the same sentence as ZNF83 in open-access papers:
ZNF83 is named in the same sentence as 8 diseases in open-access papers, as found by Europe PMC text mining. Sharing a sentence is not in itself a finding about the gene and the disease. The quoted sentences say what the papers report.
leukoplakia (1 paper, 2023). A white patch or plaque on a mucous membrane that cannot be characterized clinically or pathologically as any other disease. "We found 4 genes (LY75, ZNF83, ZNF160, ZNF331) common in leukoplakia and OSCC, while 9 genes appeared only in OSCC, suggesting their role in disease advancement." (PMID 37245006, 2023).
liver fibrosis (1 paper, 2025). "Our study demonstrates that ZNF83 is upregulated in human liver fibrosis." (PMID 40943308, 2025).
cancer (2 papers, 2009 to 2023). A tumor composed of atypical neoplastic, often pleomorphic cells that invade other tissues. "The possible association existing between ZNF83, TNPO2, ZFYVE1 and cancer was discussed in the present study for the first time." (PMID 19171046, 2009). "Some circRNAs implicated in oxidative stress and inflammation-related disorders are circ-PRKCA, circ-ZNF83, circ-PLEKHM3, circ-FNDC3B, circ-102115 circSATB2 and circFOXM1 on which natural products modulation have been investigated in cancers and other disorders." (PMID 37168992, 2023). "Other ncRNAs involved in oxidative stress and inflammation-related disorders are circular RNAs such as circ-PRKCA, circ-ZNF83, circ-PLEKHM3, circ-FNDC3B, circ-102115 circSATB2 and circFOXM1 on which natural products modulation have been investigated on in cancers and other chronic diseases." (PMID 37168992, 2023).
infection (1 paper, 2015). The state of being infected such as from the introduction of a foreign agent such as serum, vaccine, antigenic substance or organism. "While pseudogene ZNF137P is increasingly downregulated as the infection progresses, its parent gene ZNF83, an anti-inflammatory gene, is over-expressed by a factor of 1.5 in all six datasets at 24 h post-infection, but is under-expressed seven days post-infection." (PMID 26426037, 2015).
tumor (1 paper, 2024). "The transcriptional programs regulated by TBX21, ZNF595, FOSL2, ZNF83, ZNF484, IKZF2, and ELK3 were found to be significantly activated in tumor-reactive T cells." (PMID 39243082, 2024).
ZNF83 also shares sentences with these, for which no sentence is quoted: atherosclerosis (1 paper); head and neck cancer (1); melanoma (1).